CXCR6 (C-X-C motif chemokine receptor 6)
Diseases named in the same sentence as CXCR6 in open-access papers (continued):
Sharing a sentence is not in itself a finding about the gene and the disease.
Autoimmunity (6 papers, 2019 to 2025). The occurrence of an immune reaction against the organism's own cells or tissues. "CXCR6+CD4+ T cells recently received much attention as prominent producers of cytokines and highly pathogenic effector cells during autoimmunity." (PMID 38838013, 2024). "Recently, we discovered that pathogenic CD4 T cells were CXCR6 positive in experimental autoimmune encephalomyelitis (EAE), a commonly used Th17-driven autoimmune model." (PMID 35178050, 2022). "A large proportion of CD4+ T cells that expressed GM-CSF also expressed CXCR6, but this chemokine receptor did not play a main role in the CNS autoimmunity." (PMID 40904462, 2025). "Mechanistically, IL-15 induces FOXO1 downregulation and CXCR6 upregulation, rendering liver-resident CXCR6+ CD8+ T cells sensitive to metabolic stimuli (including acetate and extracellular ATP) and collectively triggering autoimmunity, exacerbating NASH progression." (PMID 39021599, 2024).
colon cancer (6 papers, 2016 to 2023). "We explored the infiltration and prognostic value of CXCR6+TAMs in all stages of colon cancer (CC) patients and assessed predictive ability as a biomarker for different ACT regimens among high-risk stage II and stage III patients in both primary and validation cohorts." (PMID 36230570, 2022). "Therefore, our results indicate that CXCR6+TAMs could be a potential prognostic and predictive biomarker for patients with colon cancer." (PMID 36230570, 2022). "CXCR6, which was reported to be exclusively expressed on intratumoral CD8+ T cells in colon cancer, positions cytotoxic T cells to receive critical survival signals in the tumor microenvironment." (PMID 35967414, 2022). "C1 (Tumor-Treg) showed 112 DEGs between colon cancer and rectal cancer, such as TNF and CXCR3, which were up-regulated, while CXCR6 and CCR6 were down-regulated in colon cancer in comparison to that of rectal cancer." (PMID 33584715, 2020). "Circulating MAIT cells exhibited high levels of CCR6 and CXCR6, and their corresponding chemokines, such as CCL20 and CXCL16, were strongly expressed in colon cancer tissues." (PMID 27517754, 2016). "Indeed, the absence of CXCR6 in the transplantable MC38 colon tumor model drastically reduced the response to immune checkpoint therapy and decreased the number and cytotoxic effector activity of tumor-infiltrating CD8+ T cells." (PMID 36428508, 2022).
non-small cell lung carcinoma (6 papers, 2015 to 2024). A group of at least three distinct histological types of lung cancer, including non-small cell squamous cell carcinoma, adenocarcinoma, and large cell carcinoma. "JPX regulated GC development through miR-197/CXCR6 axis and yet related with non-small cell lung cancer and cervical cancer." (PMID 36567977, 2022). "Here, we present evidence that chemokine receptor CXCR6 and its only natural ligand, CXCL16, are significantly expressed by non-small cell lung cancer (NSCLC) and are involved in the pathobiology of LuCa." (PMID 25888629, 2015). "Also, in the non-small cell lung cancer model, CXCR6 was not expressed in stromal cells such as fibroblasts, endothelial cells, and macrophages." (PMID 33800554, 2021).
respiratory failure (6 papers, 2021 to 2025). The significant impairment of gas exchange within the lungs resulting in hypoxia, hypercarbia, or both, to the extent that organ tissue perfusion is severely compromised. "Different human polymorphisms have an impact on clinical outcomes: sequence changes in ApoE, TLR7, TMEM189-UBE2V1, as well as SLC6A20, LZTFL1, CCR9, FYCO1, CXCR6, XCR1, have been associated with severe disease outcomes as well as respiratory failure." (PMID 35207458, 2022).
allergic disease (5 papers, 2019 to 2025). An immune response that occurs following re-exposure to an innocuous antigen, and that requires the presence of existing antibodies against that antigen. "The downregulation of CXCR3 and CXCR6 gene expression in circulating mononuclear cells may be a marker of type 2, IgE-predominant responses associated with environmentally driven allergic disease." (PMID 33804792, 2021). "IL-4, IL-13, and IL-5 production has been demonstrated to induce clinical symptoms of asthma, including eosinophilia and airway hypersensitivity, indicating a clear role for ST2+ CXCR6+ Th2 cells in driving acute allergic disease." (PMID 41256356, 2025). "Using variant-based analyses, FYCO1, CXCR6 and NRP2 shed new light to mechanisms influencing allergy." (PMID 30206357, 2019).
Alzheimer disease (5 papers, 2023 to 2025). A progressive, neurodegenerative disease characterized by loss of function and death of nerve cells in several areas of the brain leading to loss of cognitive function such as memory and language. "This study reported that CXCL16/CXCR6 crosstalk between microglia and T cells restricted Alzheimer’s disease pathology due to their immunosuppressant activity." (PMID 38005878, 2023). "Another recent study found that CXCL16/CXCR6 signaling orchestrated the retention of resident memory T cells within the brains of human Alzheimer’s disease patients and mouse models of Alzheimer’s disease." (PMID 38005878, 2023). "A previous study revealed that CXCR6 coordinates the residence of CD8+ T cells in the brain and limits the progression of Alzheimer’s disease in mice." (PMID 40715695, 2025).
asthma (5 papers, 2019 to 2025). "CXCR6 encodes for a chemokine receptor expressed on the surface of multiple immune cell types and was associated with asthma and Th2 inflammation in the lung." (PMID 30206357, 2019). "Then, CXCR6 deficiency could be detrimental in case of asthma inflammation where it sustains type 2 response by the decrease of restricting type 1 secretion but limits the possible epithelial wound healing." (PMID 31690060, 2019). "Similarly, CXCR6 was expressed on lung-infiltrating Th2 cells in a mouse model of asthma and in asthmatic patients." (PMID 32075873, 2020). "This biomarker is produced in large quantities by alveolarmacrophages in the bronchial epithelium, and expression of its receptor (CXCR6) isincreased in the BALF and T cells of individuals with asthma and sarcoidosis." (PMID 39606764, 2024).
experimental autoimmune encephalomyelitis (5 papers, 2013 to 2025). An autoimmune demyelinating disease of the central nervous system that is produced experimentally in animals by the injection of homogenized brain or spinal cord in Freund's adjuvant. "Interestingly, CD4+ T cells needed to be primed by NLRP3 inflammasome-sufficient antigen-presenting cells to upregulate chemotactic proteins such as osteopontin, CCR2, and CXCR6 in experimental autoimmune encephalomyelitis (EAE)." (PMID 36766797, 2023). "CXCL16 has also been shown to regulate T cell homing to the CNS in experimental autoimmune encephalomyelitis (EAE), and it was recently shown in this model that immature myeloid cells expressing CXCL16 redirect CXCR3 + CXCR6+ and myelin-specific T cells from CNS to lymph nodes." (PMID 24069377, 2013).
lymph node metastasis (5 papers, 2019 to 2022). "Studies have shown that the expression of CXCR6 is associated with lymph node metastasis, and the same conclusions have been obtained in cell experiments." (PMID 33829065, 2021). "The expression of CXCR6+TAMs was higher in lymph node metastasis and distant metastasis groups." (PMID 36230570, 2022).
malaria (5 papers, 2017 to 2026). Malaria is a serious and sometimes fatal disease caused by a parasite that commonly infects a certain type of mosquito which feeds on humans. "Among children living in malaria-endemic Uganda, CXCR6+ CD127− Tr1 cells were the dominant responding subset to Pf-infected red blood cell stimulation in vitro." (PMID 41000872, 2025). "Using this higher-resolution definition, we evaluated surface markers and found that CXCR6+ CD127− cells effectively enriched for Tr1 cells in malaria-exposed children." (PMID 41000872, 2025). "Altogether, these data highlight the clinical relevance of CXCR6+ CD127− Tr1 cells as a functionally suppressive cell subset that likely aids in the acquisition of clinical immunity to malaria but may facilitate parasite persistence." (PMID 41000872, 2025). "Here, we utilized single cell RNA sequencing to identify putative cell surface markers for Tr1 cells in the blood of children living in malaria-endemic Uganda and establish that CXCR6+ CD127− memory CD4+ T cells enrich for high-confidence, bona fide Tr1 cells in this setting." (PMID 41000872, 2025). "After establishing that CXCR6+ CD127− Tr1 cell were the predominant CD4+ T cell population responding to malaria in children, we leveraged the longitudinal, paired nature of the MUSICAL clinical study to determine whether these cells correlated with clinical outcomes of infection." (PMID 41000872, 2025). "We further demonstrate that CXCR6+ CD127− Tr1 cells are functionally suppressive, respond to Plasmodium antigens in vitro and in vivo, and correlate with systemic responses to malaria." (PMID 41000872, 2025). "In this study, we demonstrated that CXCR6 and CD127 can be used to enrich for Tr1 cells in the peripheral blood of malaria-exposed Ugandan children." (PMID 41000872, 2025). "We identified CXCR6 and CD127 as effective markers for enriching for Tr1 cells in a specific tissue and clinical context—the blood of malaria-exposed humans." (PMID 41000872, 2025). "Our data demonstrate that CXCR6+ CD127− Tr1 dominate the response to Pf infected red blood cell antigens, rapidly expand following malaria in vivo, and express IL-10 and IFNγ in vivo during both symptomatic malaria and asymptomatic parasitemia." (PMID 41000872, 2025). "In sum, these data confirm that CXCR6+ CD127− Tr1 cells are functionally suppressive and may therefore influence clinical immunity to malaria." (PMID 41000872, 2025). "By validating new cell surface markers (CXCR6+ CD127−) using scRNAseq and functional experiments to identify high-confidence, bona-fide Tr1 cells, we were able to study the function and clinical relevance of Tr1 cells among children living in malaria-endemic Uganda." (PMID 41000872, 2025).
ovarian tumor (5 papers, 2021 to 2024). "To corroborate the human findings of preferential expression of CXCR6 on ovarian tumor-infiltrating Trm cells, we used prophylactic vaccine models in murine ovarian tumors." (PMID 34607898, 2021). "Further, the observation of proximity of CD103+ T cells to cells that express CXCL16 (the primary chemokine ligand for CXCR6) serves as additional evidence for the role of CXCR6 in Trm cell localization in ovarian tumor tissues." (PMID 34607898, 2021). "The deletion of CXCR6 in tumor-specific CD8+ T cells resulted in reduced retention in tumor tissues and increased CD8+ T-cell recirculation to the spleen, culminating in diminished resident memory response and reduced control of ovarian tumors." (PMID 34607898, 2021).
tuberculosis (5 papers, 2014 to 2021). A chronic, recurrent infection caused by the bacterium Mycobacterium tuberculosis. "Pulmonary vaccination with an adenovirus-vectored tuberculosis (TB) vaccine resulted in increased expression of CXCR6 on lung localized CD8+ T-lymphocytes that were associated with protection against M. tuberculosis." (PMID 30899256, 2019). "Studies by Lee and collaborators indicated that expression of CXCR6 on lung T cells after immunization is a marker for local protective immunity to tuberculosis and that this receptor and CXCL16 play an important role at localization of T cells." (PMID 32218590, 2020). "In addition, we characterized the immune phenotype and expression of CXCR6 in circulating NK cells from humans with distinct clinical forms of tuberculosis (TB)." (PMID 33117393, 2020).
cervical cancer (4 papers, 2021 to 2023). A primary or metastatic malignant neoplasm involving the cervix. "Moreover, the CXCL16/CXCR6 complex may be useful as a biomarker and a valuable prognostic factor for cervical cancer." (PMID 34833360, 2021). "A new cytokine (CXCL16) was investigated together with the chemokine receptor combination CXCL12/CXCR4 and CXCL16/CXCR6 in cervical intraepithelial neoplasia (CIN) and cervical cancer." (PMID 34833360, 2021).
Hepatitis (4 papers, 2012 to 2024). Inflammation of the liver. "These roles are underscored by human HBV data which show higher CREM activity in HBV-specific CXCR6+ CD8 T cells in patients with active hepatitis and less CREM activity with increasing viral control and absence of liver damage." (PMID 38987588, 2024). "VCAM-1 and CXCL16 increased expression led to the recruitment of CXCR6+ cells by the liver, perpetuating the bystander hepatitis." (PMID 23110209, 2012). "Therefore, stimulation of TLR3 and 9 promotes homing of CXCR3+ and CXCR6+ T cells, including autoreactive T cells, resulting in bystander hepatitis." (PMID 23110209, 2012). "Previous studies confirmed that CXCR6 and secreted soluble CXCL16 might be responsible for inducing chemotactic migration of proinflammatory cells into arthritic joints and sites of liver inflammation." (PMID 24460887, 2014). "Instead CXCR6+ NK could upregulate TRAIL, a key death ligand in hepatitis pathogenesis." (PMID 27210614, 2016).
HIV-1 infection (4 papers, 2014 to 2022). The type species of lentivirus and the etiologic agent of acquired immunodeficiency syndrome (AIDS). "Alongside CD69, resting memory T cells also increased co-expression of the TRM marker CXCR6 during HIV-1 infection." (PMID 35417711, 2022). "CXCR6-tropism has been reported for some T/F viruses in infected infants, even though CXCR6 is considered a minor contributor to HIV-1 infection in general." (PMID 33499233, 2021). "Entry via CXCR6 in some primate hosts may target SIV towards cells that may support viremia without causing immunodeficiency, but this pattern was lost during the emergence of pathogenic SIVcpz and HIV-1 infections." (PMID 29659623, 2018). "Strikingly, blocking STAT5 activity in this way completely inhibited induction of the TRM phenotype by HIV-1 infection, preventing upregulation of CD69 and CXCR6." (PMID 35417711, 2022). "Finally, we assessed whether the expression of other co-receptors, CXCR6, CCR5 and CXCR4, also was modulated in the context of HIV-1 infection." (PMID 24558379, 2014).
lung adenocarcinoma (4 papers, 2019 to 2025). A carcinoma that arises from the lung and is characterized by the presence of malignant glandular epithelial cells. "In lung adenocarcinoma, recent studies have confirmed that AXL inhibition decreased the expression of PD-L1 and CXC chemokine receptor 6 (CXCR6), especially when EGFR was mutated." (PMID 31703465, 2019). "CXCR6 is a potential prognostic biomarker in lung adenocarcinoma." (PMID 38698468, 2024).
nasopharyngeal carcinoma (4 papers, 2009 to 2024). A carcinoma arising from the nasopharyngeal epithelium. "The high expression of CXCR6 on LCL-derived VST is consistent with a previous study where CXCL16 secretion from nasopharyngeal carcinoma recruited CXCR6high T cells to the tumor site." (PMID 39011042, 2024). "In tumors such as nasopharyngeal carcinoma, renal cell carcinoma Treg show higher expression of CXCR6 compared to blood Treg." (PMID 33800554, 2021).
Obesity (4 papers, 2022 to 2025). Accumulation of substantial excess body fat. "Monocytes and macrophages appear to be associated with adiposity in patients with obesity and COVID‐19, with CD14+CXCR6+ cells positively correlated with the elevated BMI and CD68+ cells in the epicardial adipose tissue." (PMID 35837843, 2022). "Using the terms, hypothalamus, hypothalamic, obesity, inflammation, Cxcr3, and Cxcr6, we could find no prior publications." (PMID 39535032, 2024).
sarcoidosis (4 papers, 2009 to 2024). Sarcoidosis is a multisystemic disorder of unknown cause characterized by the formation of immune granulomas in involved organs. "Among chemokine receptors, mRNA expressions of CCR2-var.A (P = 0.018), CCR5 (P = 0.003), CXCR3 (P < 0.001), and CXCR6 (P < 0.001) were elevated in sarcoidosis patients." (PMID 26696750, 2015). "We and others have shown that the chemokine receptor, CXCR6, is highly expressed on lung derived T cells compared to blood T cells, especially in inflammatory diseases characterized by T-cell infiltration in the lung, such as sarcoidosis, suggesting that CXCR6 is a candidate lung homing receptor." (PMID 19415545, 2009). "The close relationships in sarcoidosis as a whole were found between T-bet and IL2RB, IL15RA, and CXCR3, which was related to CXCR6 and IFNG." (PMID 26696750, 2015). "Our correlation analysis revealed relationship of T-bet and sarcoid inflammation, namely, its association with key sarcoidosis-associated cytokine IFNG, and receptors IL2RB, IL15RA, CXCR3, and CXCR6, regardless of the disease outcome." (PMID 26696750, 2015). "While expression has been reported on T-cells in inflammatory lung disease such as sarcoidosis, our result indicate that CXCR6 is not expressed to an appreciable degree in infiltrating immune cells in NSCLC." (PMID 26021984, 2015).
Sepsis (4 papers, 2023 to 2025). Sepsis is defined as life-threatening organ dysfunction caused by a dysregulated host response to infection. "Sepsis-trained lung macrophages stimulated CCR2 and CXCR6 chemokine release, triggering T-cell tissue residency - an immune mechanism that reduced post-sepsis tumor recurrence risk." (PMID 41403926, 2025). "Sepsis‐trained resident macrophages released a chemokine network including CXCL16 triggers tissue residency of T cells via CCR2 and CXCR6 stimulations responsible for decreased risk of tumor development after sepsis cure." (PMID 39494816, 2024). "There were limited studies that focused on the role of CXCR6 plays in sepsis." (PMID 36860871, 2023).
acute myeloid leukemia (3 papers, 2021 to 2023). Acute myeloid leukemia (AML) is a group of neoplasms arising from precursor cells committed to the myeloid cell-line differentiation. "Our analysis data suggested the predictive potential of CXCR as four CXCR members (CXCR3, CXCR4, CXCR5, and CXCR6) were significantly related to better clinical outcomes in HNSCC, as reported in acute myeloid leukemia." (PMID 35978426, 2022).
AIDS (3 papers, 2011 to 2021). A syndrome resulting from the acquired deficiency of cellular immunity caused by the human immunodeficiency virus (HIV). "In particular, the presence of specific polymorphisms in CXCR6 leads to rapid progression of acquired immunodeficiency syndrome (AIDS) and influences the effectiveness of highly active antiretroviral therapy (HAART)." (PMID 33800554, 2021). "Genotypes of exonic polymorphisms in chemokine coreceptor genes CCR3, CCRL2 and CXCR6 on Chromosome 3p21 and in CCR8 and CX3CR1 on 3p22 were tested for their genetic influence on AIDS progression." (PMID 22046140, 2011). "The AIDS Link to Intravenous Experience (ALIVE) study, a prospective cohort study of predominantly African American HIV-infected drug users, examined the relationship of CXCR6 SNPs and development of PCP." (PMID 30815637, 2018).
autoimmune disease (3 papers, 2024 to 2025). A disorder resulting from loss of function or tissue destruction of an organ or multiple organs, arising from humoral or cellular immune responses of the individual to their own tissue constituents. "Therefore, the CXCL16/CXCR6 axis may be a potential therapeutic target for tumors, kidney diseases, cardiovascular diseases, non-alcoholic fatty liver disease 43, and autoimmune diseases." (PMID 40722833, 2025).